ZMYND8 (zinc finger MYND-type containing 8)
Diseases named in the same sentence as ZMYND8 in open-access papers (continued):
Sharing a sentence is not in itself a finding about the gene and the disease.
breast carcinoma (continued). "Again, mRNA expression levels of PYGO2 and KDM5B were higher in Luminal, HER2+, and basal-like breast cancers, and ZMYND8 was higher in Luminal B and HER2+ subtypes compared with that in the normal-like subtype in the METABRIC dataset (p < 0.001)." (PMID 28055972, 2017). "We also found that Luminal B breast cancer had the highest frequency of ZMYND8 gain/amplification in the METABRIC dataset." (PMID 28055972, 2017). "We found that most ZMYND8-amplified breast cancer samples also showed the amplification of other candidate oncogenes at the 20q13 region." (PMID 28055972, 2017). "A finding of particular interest from our study is the dysregulation of ZMYND8 in a subset of breast cancers." (PMID 28055972, 2017). "High expression of ZMYND8 was significantly correlated with patient survival and was likely involved in a positive feedback circuit of the ER pathway in breast cancer." (PMID 28055972, 2017). "Western blot also revealed the additional protein bands with molecular weight lower than full-length ZMYND8 in breast cancer cell lines, particularly Luminal subtypes." (PMID 28055972, 2017). "Based on this, we hypothesized that ZMYND8 in breast cancer cells may promote immunosuppression by regulating macrophage recruitment and polarization." (PMID 41297414, 2025). "Furthermore, immunohistochemistry analysis also shows that ZMYND8 and HIF1α expression are positively correlated in breast cancer." (PMID 40912652, 2025). "Further research is needed to explore whether ZMYND8-mediated NRF2 activation in BCSCs can promote resistance to therapies in breast cancer." (PMID 40214466, 2025). "Interestingly, ZMYND8-induced changes in metabolic intermediate lactate in breast cancer cells, as well as in mouse serum, significantly impact the immune cell invasion and CD8+ T cell activity in the tumor microenvironment." (PMID 40912652, 2025). "Further analysis of the relationship between ZMYND8 expression and clinicopathological features showed that high ZMYND8 expression was positively correlated with advanced tumor stage and lymph node metastasis, implying its involvement in breast cancer progression." (PMID 41297414, 2025). "ZMYND8, recognized as a core component of various transcriptional regulatory complexes, has demonstrated significant tumor-suppressive effects in breast cancer and prostate cancer in previous studies, providing evidence for its potential as a biomarker candidate in this research." (PMID 40894525, 2025). "Notably, ZMYND8 is overexpressed in breast cancer, where it promotes metastasis through dysregulation of HIF signaling, the cGAS-STING pathway, and cholesterol metabolism." (PMID 41297414, 2025). "Thus, ZMYND8 exon 22 inclusion can play a pivotal role in shaping clinical outcomes for breast cancer patients." (PMID 38539439, 2024). "Given that ZMYND8 has been shown to promote radioresistance in glioma, it would be interesting to study whether ZMYND8-mediated NRF2 activation in BCSCs could promote resistance to therapies in breast cancer." (PMID 38488001, 2024). "Thus, we believe that ZMYND8 would be an effective therapeutic target for the treatment of breast cancer and other human cancers with high activation of NRF2." (PMID 38488001, 2024). "Our previous study showed that ZMYND8 physically interacts with p300 in breast cancer cells." (PMID 38488001, 2024). "In addition to its role in breast cancer, ZMYND8 is upregulated and promotes tumor growth in multiple cancer models, including acute myeloid leukemia, bladder cancer, clear cell renal cell carcinoma, colorectal cancer, glioblastoma, and liver cancer." (PMID 38488001, 2024). "ZMYND8 negatively regulates ferroptosis in breast cancer stem cells." (PMID 38488001, 2024). "Next, we investigated whether ZMYND8 reduced ROS to increase mammary tumor initiation in vivo by limiting dilution assay." (PMID 38488001, 2024).
breast carcinoma (continued). "In addition, ZMYND8 expression is lower in breast cancer patients with invasive ductal carcinoma than in ductal carcinoma in situ." (PMID 33670804, 2021). "However, in breast cancer cells, the expression of CDKN1A mRNA was upregulated by ZMYND8 loss, which suggests ZMYND8 depletion can increase the p21, which is an inhibitor of cell-cycle progression." (PMID 33670804, 2021). "In vivo experiments revealed that ZMYND8 increased the circulating breast cancer cells, to promote their extravasation and colonization, leading to lung metastasis in severe combined immunodeficiency (SCID) mice, whereas in ZMYND8 knockouts, these features were reversed." (PMID 33670804, 2021). "In breast cancer cells, ZMYND8 may be present as a fusion protein with centrosomal protein 250 (CEP250), which is required for centriole–centriole cohesion during interphase." (PMID 33670804, 2021). "Amplification and overexpression of ZMYND8 are more frequent in luminal B breast cancer subtypes." (PMID 33670804, 2021). "Microarray analysis of breast cancer cells with ZMYND8 knockout by siRNA revealed that depletion of ZMYND8 reduces the expression of terminal differentiation markers, such as epithelial cell adhesion molecule (EPCAM) and cytokeratin 18 (CK18), by 80% and 86%, respectively." (PMID 33670804, 2021). "Ablation of either ZMYND8 or KDM5C in ZR-75-30 breast cancer cells results in over-activation of their target enhancers, characterized by the deposition of H3K4me3 and H3K27ac, decreased H3K4me1, and increased transcription of enhancer RNAs (eRNAs) and nearby genes." (PMID 33670804, 2021). "Therefore, our study establishes ZMYND8 as a potent chemo-sensitizer that can reverse chemo-resistance in breast cancer." (PMID 33323928, 2020). "Interestingly, we observed that ZMYND8 overexpression in doxorubicin-treated cells stimulated those involved in a good prognosis in breast cancer." (PMID 33323928, 2020). "We further examined ZMYND8 expression in a panel of breast cancer cells." (PMID 28055972, 2017). "In our analysis of the genetic alterations of PHFs in breast cancer, we found that ZMYND8 had a higher frequency of amplification and overexpression in Luminal B breast cancer, and its overexpression was associated with shorter survival in patients in both TCGA and METABRIC datasets." (PMID 28055972, 2017). "Furthermore, we found that JQ-1, a bromodomain and extra terminal (BET) inhibitor, suppressed ZMYND8 expression in breast cancer." (PMID 28055972, 2017). "Interestingly, we found that ZMYND8, which physically binds ERα, is a downstream target of ERα, suggesting that ZMYND8 is in a positive feedback circuit of the ER pathway in breast cancer." (PMID 28055972, 2017). "Furthermore, the expression of ZMYND8 was repressed after treatment with the BET inhibitor JQ-1 in breast cancer cells." (PMID 28055972, 2017). "In the present study, we provided additional evidence that ZMYND8 was involved in a positive feedback circuit involving the ER pathway in breast cancer, where the interaction between ZMYND8 and ERα promotes activation of the ERα target gene, including ZMYND itself." (PMID 28055972, 2017). "Furthermore, fusion of ZMYND8 has been identified in lymphoma and breast cancer; both of the ZMYND8 fusions reportedly remove the MYND domain but retain the N-terminal PBP cassette." (PMID 28055972, 2017). "Nevertheless, one relevant signalling pathway caught our attention: the integrated breast cancer pathway, with a p-value of 0.059 in association with the circRNA circZMYND8_A, formed by the circularisation of exons 20 and 21 of the ZMYND8 gene (also called RACK7)." (PMID 38203852, 2024). "However, increased ZMYND8 expression is associated with high mortality in patients with different subtypes and stages of breast cancer, but not with different grades of tumor." (PMID 33670804, 2021).
breast carcinoma (continued). "We propose that combination therapy with inhibitor targeting KDM5C enzymatic activity and KDM5C/ZMYND8 interaction or ERα antagonist would be efficacious in battling and/or provide an additional therapeutic adjunct for ER‐positive and endocrine therapy‐resistance breast cancers." (PMID 33977073, 2021). "Using an orthotopic breast cancer model, we found that low ZMYND8 expression significantly reduced primary tumor growth in BALB/c mice, suggesting that ZMYND8 promotes breast tumor growth." (PMID 41297414, 2025). "We and others have previously shown that epigenetic coregulators such as ZMYND8, CHD4, CARM1, TRIM24, and JMJD2C are frequently amplified or upregulated to promote breast cancer progression through their role in epigenetic reprogramming." (PMID 37655663, 2023). "The p300-mediated ZMYND8 acetylation is indispensable to HIF activation and breast cancer progression and metastasis." (PMID 37691108, 2023). "For instance, Detection of epigenetic regulators, such as ZMYND8, E2F1 and KDM6A, would be beneficial for determining prognosis and management in breast cancer patients." (PMID 36967443, 2023). "In human breast cancer tissues, the expression of TROJAN negatively correlates with ZMYND8 expression, and it positively correlates with EGFR, VEGF-A, and MDM2 expression." (PMID 33670804, 2021). "In breast cancer cells, HIF-1 and HIF-2 can induce ZMYND8 expression, and HIFs and ZMYND8 co-activate oncogenes and increase RNA polymerase II phosphorylation, leading to the promotion of cell motility, tumor growth, and lung metastasis." (PMID 33670804, 2021). "In MDA-MB-231 LM2 breast cancer cells, TROJAN binds to ZMYND8, and increases its degradation through the ubiquitin-proteasome pathway, by repelling ZNF592." (PMID 33670804, 2021). "ZMYND8 knockdown increases the expression of Ki67 and PCNA by about 14 and 4 folds, respectively, in HeLa cells; about 8 and 3 folds in MCF7 breast cancer cells; and about 9 and 2.5 folds in T47D metastatic breast cancer cells." (PMID 33670804, 2021). "Suppression of migration and invasion by ZMYND8 in breast cancer cells is through cooperation with KDM5C and modulation of SA100, as knockout of ZMYND8 or KDM5C can de-repress S100A." (PMID 33670804, 2021). "In an attempt to define novel functions of ZMYND8 in cancer, we analyzed a published RNA-seq dataset derived from ZMYND8 wild-type (WT) and knockout (KO) MDA-MB-231 breast cancer cells." (PMID 33593912, 2021). "In the Matrigel invasion assay, ZMYND8 knockout results in a 1.6-2-fold increase in the invasiveness of HeLa and MCF7 breast cancer cells, and its overexpression reduces the invasiveness by 1.3–1.5 folds in these two cells." (PMID 33670804, 2021). "The influence of ZMYND8 on cancer cell invasion and metastasis is related to the interaction between ZMYND8, TROJAN, and ZNF592 in breast cancer." (PMID 33670804, 2021). "A recent paper showed that ZMYND8/RACK7 interacts directly with HIFα and BRD4 to promote transcription elongation of some HIF target genes in breast cancer cells." (PMID 32286255, 2020). "Our findings showed that ZMYND8 is instrumental in recruiting corepressors, KDM5C, and EZH2 onto their target promotors to regulate tumor-genes in breast cancer." (PMID 33323928, 2020). "Among 11 most commonly amplified/overexpressed PHF genes, we found that three genes, ZMYND8, PHF20, and DIDO1, were significantly highly expressed in advanced-stage breast cancers (T-test: Stage I+II vs III+IV; p < 0.05)." (PMID 28055972, 2017). "The upstream sequence of exon 22 of CEP250 gene (ENST00000356095) was searched for in breast cancer cell line BT474, and was found to be a sequence from exon 16 to exon 19 of ZMYND8 gene (ENST00000360911)." (PMID 24533689, 2014). "Further analysis revealed that ZMYND8 expression was markedly elevated at both the mRNA and protein levels in human spinal metastatic tissues compared to primary breast cancer lesions and matched adjacent non-tumor tissues." (PMID 41297414, 2025).
breast carcinoma (continued). "Both ZMYND8 and DHCR24 promote breast cancer stem cell survival." (PMID 39757707, 2025). "The regulons SPIB, STAT4, and ZMYND8 were seen as the master regulators of immune modulation in PRLR-low patients who did not experience early breast cancer events." (PMID 40723262, 2025). "Conclusions were that CHD4 coactivates HIF to promote breast tumor growth, and that different mRNAs were also up-regulated in human breast tumors (ZMYND8, KDM4C (JMJD2C), CDK8, CREBBP (CBP), KAT), suggesting the heterogeneity of epigenetic regulation of HIF in breast cancer." (PMID 33981601, 2021). "Furthermore, in HeLa and MCF7 breast cancer cells, ATRA induces an H3K27me3 to H3K27ac switch and upregulates ZMYND8 expression." (PMID 33670804, 2021). "Intriguingly, the subset of genes that were regulated upon ZMYND8 overexpression in combination with doxorubicin treatment showed higher distant metastasis-free survival (DMFS), as assessed by Kaplan–Meier analysis in breast cancer patients." (PMID 33323928, 2020). "ZMYND8 was also involved in a positive feedback circuit of the estrogen receptor (ER) pathway, and the expression of ZMYND8 was repressed by the bromodomain and extra terminal (BET) inhibitor in breast cancer." (PMID 28055972, 2017). "Thus, ZMYND8 expression is likely regulated by multiple mechanisms, including gene amplification, ERα, and possibly BRD4 pathways in breast cancer." (PMID 28055972, 2017). "By conducting integrated genomic and transcriptomic analyses of breast cancers with different molecular subtypes and clinicopathological features, we identified a subset of PHF genes, including PGYO2, CHD3, and ZMYND8, that have high frequencies of CNA and altered mRNA expression." (PMID 28055972, 2017). "Notably, this effect was not attributable to changes in the intrinsic proliferative capacity of tumor cells, as ZMYND8 knockout did not alter breast cancer cell proliferation in vitro." (PMID 41297414, 2025). "ZMYND8 is also involved in genome stability to block the cyclic GMP–AMP synthase-stimulator of interferon genes–NF-κB signaling and the subsequent interferon-β production in breast cancer cells, leading to cancer cell evasion from cytotoxic T-lymphocyte surveillance." (PMID 38488001, 2024). "These analyses indicate that ZMYND8 overexpression in MDA-MB-231 cells treated with doxorubicin significantly alters the tumor/cancer-related gene levels and signaling pathways specific to aggressive breast cancer, and suggests the role of ZMYND8 in chemo-resistance." (PMID 33323928, 2020). "However, ZMYND8 could not rescue the proliferation inhibition caused by TROJAN knockdown in MCF7 cells, indicating that TROJAN did not participate in the ZMYND8-mediated pathway in ER+ breast cancer." (PMID 32393270, 2020). "We found that ZMYND8 and PHF20, but not DIDO1, also had significantly higher expression in advanced stages of Luminal breast cancers (p < 0.05)." (PMID 28055972, 2017). "We also found that ZMYND8 has a higher expression level in Luminal and HER2+, but not in the basal-like subtype, compared with that in the normal-like subtype breast cancer." (PMID 28055972, 2017). "An in vitro study also showed that ZMYND8 knockdown by small interfering RNA (siRNA) suppressed colony formation and reduced the number of MCF-7 breast cancer cell colonies; however, ZMYND8 knockdown did not affect the proliferation rate of the breast cancer cells." (PMID 33670804, 2021).
breast tumor (7 papers, 2020 to 2025). "Gene expression analysis in the Cancer Genome Atlas (TCGA) cohort revealed that ZMYND8 mRNA significantly correlated with the gene signature of glutathione metabolic process in human breast tumors." (PMID 38488001, 2024). "Pair-wise mRNA expression correlation analysis in human breast tumors from TCGA cohort showed a positive correlation between ZMYND8 and antioxidant genes including NQO1, GPX2, GCLC, GCLM, TXNRD1, and SRXN1." (PMID 38488001, 2024). "Our previous studies showed that ZMYND8 blocks T-lymphocyte surveillance to promote breast tumor growth." (PMID 38488001, 2024). "The modest gene correlations between ZMYND8 and glutathione metabolic gene signature or antioxidant genes in TCGA breast tumors are likely due to limitations of analysis of overall gene expression in the mixed cell populations." (PMID 38488001, 2024). "Our recent study has identified a role of ZMYND8 in maintenance of BCSCs and breast tumor initiation." (PMID 38488001, 2024). "Lastly, we performed gene correlation analysis in human breast tumors to support positive regulation of NRF2 target genes by ZMYND8." (PMID 38488001, 2024). "Notably, aberrant accumulation of ZMYND8 has been observed in breast tumors, yet the mechanisms enabling its stabilization in malignancy are poorly defined." (PMID 41297414, 2025). "Further, Kaplan–Meier analysis showed that ZMYND8 independently or in the presence of low dose of doxorubicin, induced gene expression profiles that are associated with better DMFS, and these genes are preferentially expressed in normal-like or low grades of breast tumors." (PMID 33323928, 2020). "We found a positive correlation between ZMYND8 and NFE2L2 mRNAs in human breast tumors and 28 other types of human cancers from TCGA cohort." (PMID 38488001, 2024).